MIR4522 (microRNA 4522)
Synonyms: hsa-mir-4522
Gene: MicroRNA gene on chromosome 17 (27,293,910 to 27,293,996, reverse strand). Ensembl gene ENSG00000263583.
Homologues: Orthologues: chimpanzee MIR4522 (100% identical).